CCL18 (C-C motif chemokine ligand 18)
Diseases named in the same sentence as CCL18 in open-access papers (continued):
Sharing a sentence is not in itself a finding about the gene and the disease.
tumor (continued). "CCL18, the most abundant and specific chemokine released from TAMs, plays a crucial role in the recruitment of immune cells towards tumour sites, which is essential for tumour angiogenesis and endothelial cell survival." (PMID 40852716, 2025). "In the tumor microenvironment (TME), macrophages are divided into two main subsets: C1Q+ and SPP1+ tumor-associated macrophages (TAMs), as well as two secondary subsets: FCN1+ and CCL18+ TAMs." (PMID 40034694, 2025). "These visualizations confirm the strength and consistency of the observed associations and support the hypothesis that both CCL18 and EGF integrate into broader transcriptional programs relevant to tumor behavior." (PMID 40692603, 2025). "CCL18 was considered as a marker of macrophages M2, and its high expression predicted poor prognosis for tumor patients, which may be related to immune escape of tumor cells and immunosuppression of tumor microenvironment." (PMID 40435311, 2025). "Notably, CCL18+ macrophages were preferentially enriched in tumors compared with paired peri-tumor tissues." (PMID 41409288, 2025). "Expression of CCL18, IL-5RA, and HLA-B as well as macrophage tumor infiltration could identify patients who can potentially benefit from treatment with immune checkpoint inhibitors." (PMID 38790160, 2024). "The immune escape of tumor cells can also be induced by CCL18 and TGFB1." (PMID 39272860, 2024). "Furthermore, it was observed that tumor ECM-educated macrophages effectively promoted cancer cell invasion through a mechanism involving CCL18, as demonstrated by Matrigel invasion assays." (PMID 38221607, 2024). "In addition, compared with neighboring tissues, CTLA4+CD8+T, SPP1+ macrophages and MRC1(CD206)+ CCL18+ macrophages were also enriched in tumor tissues in the samples of colorectal cancer liver metastasis." (PMID 38279145, 2024). "The results revealed that the metabolism of MRC1 CCL18+ M2-like macrophages was the highest, suggesting that inhibiting the metabolic pathway may also slow tumor progression." (PMID 38649887, 2024). "In ESCC, advanced analyses integrating single-cell transcriptomic sequencing with bulk microarray data have uncovered that CCL18, released by TAMs, drives tumor cell proliferation via the JAK2/STAT3 signaling pathway, correlating with a poorer prognosis in ESCC." (PMID 39286635, 2024). "Additionally, under hypoxic and lactate-stimulated conditions, TAMs can secrete cytokines such as IL-6, CCL5, and CCL18 to promote glycolysis in tumor cells." (PMID 38714539, 2024). "Thus, the concentration of the cytokines CCL2, CCL5, CCL18, and TGFB1 in the CSF was associated with tumor size in patients." (PMID 39272860, 2024). "The comprehensive TME and immune landscape analyses allow us to identify the chemokine CCL18 (Chemokine C–C motif ligand 18) derived from TAMs, which could promote tumor cell proliferation and lead to poor prognosis of ESCC." (PMID 36850011, 2023). "Manipulated TAMs thus gain secretion of various tumor-promoting factors including CCL18, IL-10, and TGF-β while inhibiting the release of cytotoxic factors like IL-2, IL-12, TNF-α, and IFN-γ, impeding the anti-tumor capacity of other immune components and prolong tumor survival." (PMID 38274812, 2023). "Moreover, we observed a substantially increased proportion of LAM1/2/3 cells in tumor tissues, of which the CCL18+ LAM3 cells were predominantly present in HM tissues." (PMID 37612267, 2023). "In OC, TAMs are predominantly M2 macrophages that produce and secrete anti-inflammatory/immunosuppressive cytokines such as IL-10 and transforming growth factor beta 1(TGFB1) and chemokines (CCL17, CCL18, and CCL22) associated with tumor invasion, angiogenesis, metastasis, and early recurrence." (PMID 37298230, 2023). "Our findings further expand our knowledge of extensive PITPNM3 expression and its functional role in the tumor microenvironment, suggesting that CCL18-PITPNM3 could be an attractive therapeutic target in the tumor microenvironment." (PMID 36418470, 2023).
tumor (continued). "Consequently, these macrophages enhance tumor progression and metastasis by secreting high amounts of chemokine (C-C motif) ligand 18 (CCL18) and transforming growth factor beta 1 (TGFβ1)." (PMID 37190141, 2023). "This immunosuppressive pattern was observed in the activated TME and CCL18 may serve as one of many mechanisms bridging PDAC tumor subtypes with stromal subtypes." (PMID 37633924, 2023). "Interestingly, the introduction of IL-6 and IL-8 shRNAs into CCL18-activated NBFs significantly increased the chemotherapy-induced apoptosis of cocultured tumor cells." (PMID 36418470, 2023). "CCL18 produced by TAM attracts naïve T cells to the tumor site, resulting in T-cell anergy." (PMID 38035101, 2023). "Also, a positive feedback loop generated by tumor-shed GMCSF activates TAM to release CCL18, supporting EMT." (PMID 38035101, 2023). "In the tumor, CCL18 chemokine produced by CCL18+ TAMs was a marker of neoplastic diseases." (PMID 38347955, 2023). "The peptide Pep3 could inhibit the proliferation of EC-109 cells promoted by CCL18 and significantly restrain the tumor progression in 4-NQO-induced spontaneous ESCC mouse model." (PMID 36850011, 2023). "However, there is very few studies on the effects on tumor development through blocking the activity of CCL18." (PMID 38347955, 2023). "We also identify specific subtypes of stromal and immune cells critical to the formation of the pro-tumor microenvironment in metastatic lesions, including RGS5+ cancer-associated fibroblasts, CCL18+ lipid-associated macrophages, S100A8+ neutrophils and FOXP3+ regulatory T cells." (PMID 37612267, 2023). "Moreover, surgical trauma has been shown to induce CCL18 levels, which in turn increases tumor-site Tregs to further suppress tumor immunity." (PMID 35634302, 2022). "In the tumor microenvironment, TAMs‐derived CCL18 binds to PITPNM3." (PMID 36285700, 2022). "Additionally, macrophages differentiated within tumor decellularized matrices stimulated CRC cell invasion through the expression of CCL18, an immunosuppressive chemokine identified as a key molecule in this process." (PMID 35053521, 2022). "The results showed that CCL18 expression was higher in the GBM tumor than in the peritumoral area." (PMID 35955670, 2022). "In addition, the results of multivariate analysis of OS and DFS showed that CCL18 and tumor stages were independent prognostic factors, which are consistent with our current prognostic results on OC." (PMID 34995016, 2022). "Thus, the triad of CD8, CD68 and CCL18 clearly influences tumor prognosis, which corroborates our findings in the cox regression analysis." (PMID 35675033, 2022). "Finally, three tumor microenvironment-related genes (ADGRE1, CCL18, and LILRA6) significantly associated with PCPG prognosis were obtained by survival analysis." (PMID 33795528, 2021). "Microvascular density in tumor xenografts treated with CCL18 is higher than that in the control." (PMID 33783686, 2021). "Neutralizing antibodies towards CCL18 do not only block its effects on tumor angiogenesis though VEGF-independent mechanisms, but may also improve the response to other anti-angiogenic therapies via TAM-driven processes." (PMID 34926282, 2021). "Blocking CCL18 in tumor-bearing mice reduced intratumoral Treg numbers and inhibited tumor growth." (PMID 34632244, 2021). "Collectively, there were two kinds of immunosuppressive TAMs in the NSCLC tumor microenvironment, of which CCL18+ Macrophage used oxidative phosphorylation as the main metabolic mode and exerted immunosuppressive effects by inhibiting the production of inflammatory factors." (PMID 34804043, 2021). "Moreover, another study revealed that CCL18 affected the replicative ability of tumor cells by promoting cell transformation and altering the number of tumor cell chromosomes." (PMID 33795528, 2021). "This suggests that miR-128 may regulate the tumorigenic process of UCs by regulating CCL18 secretion from BUC T24 in the tumor microenvironment." (PMID 35059433, 2021).
tumor (continued). "Besides this, similar to PD-L1, CCL18 and BCL2A1 were also significantly positively correlated with TME score (stromal, immune, and ESTIMATE scores), whereas negatively associated with tumor purity." (PMID 35265629, 2021). "Our study innovatively found that miR-128 could influence the tumor process of the UCs by regulating CCL18 secretion." (PMID 35059433, 2021). "It is reported that the role of CCL18 in tumors appears after TAM involvement into the tumor niche." (PMID 34354751, 2021). "Taken together, we assumed that CCL18 knockdown played a role as a tumor suppressor in HB cells." (PMID 34354751, 2021). "Notably, CD3+, CD4, and CD8+ TILs were shown to secret pro-inflammatory cytokines and suppress tumor growth, whereas cancer cells were found to produce CCL18, which increases migration of regulatory T cells to tumor sites and promotes tumor progression." (PMID 32455995, 2020). "This means that the effect of CCL18 in the tumor appears after TAM recruitment to the tumor niche." (PMID 33114763, 2020). "However, to date (second half of 2020), there is only one study focusing on the effects that blocking the activity of CCL18 would have on tumor development." (PMID 33114763, 2020). "Nevertheless, TAMs are responsible for the production of CCL18 in the tumor." (PMID 33114763, 2020). "The recruitment of naïve T cells by CCL18 has been confirmed in tumor models." (PMID 33114763, 2020). "In the advanced malignant tumor, chemokines such as CCL5 and CCL18 could enhance adhesion and mobility of cancer cells to accelerate tumor invasion and metastasis." (PMID 32134471, 2020). "In a tumor, CCL18 also indirectly influences TAMs and thus its own synthesis." (PMID 33114763, 2020). "In vitro studies have shown that CCL18 is mainly produced by TAMs in the neoplastic tumor." (PMID 33114763, 2020). "A surgical laparotomy on CT26 tumor-bearing mice results in the upregulation of CCL18." (PMID 33353113, 2020). "This leads to an increase in the production of CCL18 in the vicinity of the tumor cells." (PMID 33114763, 2020). "This indicates that CCL18 plays an important pro-tumor role in these types of cancer." (PMID 33114763, 2020). "Consequently, elevated levels of CCL18 in the serum and the tumor are connected with a worse prognosis for the patient." (PMID 33114763, 2020). "The mechanism of the pro-tumor activity of CCL18 can be divided into two aspects." (PMID 33114763, 2020). "CCL18 knockdown significantly reduced tumor growth and angiogenesis." (PMID 33353113, 2020). "Collectively, our study suggests that CCL18 might be an effective indicator for angiogenesis and tumor growth and a potential target for cancer treatment towards postsurgical recovery." (PMID 30216450, 2019). "Similarly, a higher vessel density was observed in tumor tissues of laparotomy group, whereas knockdown of CCL18 suppressed laparotomy‐induced angiogenesis." (PMID 30216450, 2019). "Furthermore, a positive relationship was found between the Foxp3 level and the CCL18 level in tumor tissues (R2 = 0.1098, p = 0.035)." (PMID 30216450, 2019). "CCL18 may directly or indirectly promote tumor angiogenesis, suppress anti-cancer immune response and reshape TME, leading to malignant progression in diverse solid human cancers." (PMID 31839826, 2019). "In addition, tumor migration is upregulated by macrophage-derived cathepsins, SPARC, or CCL18, that enhance tumor cell adhesion to extracellular matrix proteins." (PMID 31684193, 2019). "We thus investigated whether upregulated CCL18 promotes the recruitment of Tregs into tumor tissues." (PMID 30216450, 2019). "Next, we addressed whether aberrant CCL18 expression was a reason for tumor growth and angiogenesis." (PMID 30216450, 2019). "Furthermore, CCL18 produced by TAMs in MF at the invasive margin of the tumor promote the recruitment of CTCL cells, leading to cancer progression." (PMID 29410946, 2018). "Naive CD4+ T cells adhered to the tumor slices in proportion to the number of CCL18+ TAMs." (PMID 28290464, 2017).
tumor (continued). "In addition, macrophage-derived cathepsins, SPARC, or CCL18 enhances the tumour cell adhesion to extracellular matrix proteins and promotes tumour cell migration." (PMID 28210073, 2017). "Moreover, TAM derived TGF-β, PGE2, IL-10, and cytokines such as CCL2, CCL17 and CCL18 recruit abundant Tregs to tumor cells." (PMID 29152078, 2017). "Moreover, recent studies have indicated that TAMs and tumor-associated neutrophils (TANs) can also contribute to tumor cell egress and survival via NCOA1, CCL18, VCAM1, ICAM1 etc." (PMID 28591712, 2017). "We found that the medium of macrophages treated with the CM derived from AXL-expressing cells, especially from mesenchymal-like cells, was enriched for tumor-promoting mediators, including CCL18, and IL-10, compared with that from macrophages treated with MCF-7-CM." (PMID 28721387, 2016). "We hypothesized that CCL18 may also be involved in tumor angiogenesis and promote resistance to anti-VEGF monotherapy." (PMID 26416449, 2015). "Additionally, other cytokines (TGF-β, IL-10, CCL18, etc.)which can be released from TAMs also have the ability to promote tumor progression through the PI3K/Akt pathway." (PMID 26359357, 2015). "In order to validate the in vitro findings, we conducted in vivo experiments to test whether CCL18 could act as a tumor promoter in RM-1 homografts of mouse model." (PMID 25197632, 2014). "It is conceivable that CCL18 can act in a paracrine fashion during tumor initiation/establishment." (PMID 25197632, 2014). "We found that CCL18 could promote tumor growth in vivo by enhancing angiogenesis and expression of cell proliferation markers PCNA and Ki67." (PMID 25197632, 2014). "As the lung is the organ with the highest level of CCL18 production, this effect might influence the homing of CCL18 responsive tumor cells to the lung." (PMID 23349697, 2013). "In addition, multivariate analysis of the data of our tumor patients indicated that CCL18 depends on tumor stage but is independent from age, gender and FEV1 (data not shown)." (PMID 22848587, 2012). "In addition, we found also a weak but significant correlation of serum CCL18 with the tumor volume, indicating that serum CCL18 that tumor size is at least one factor determining CCL18 serum concentrations." (PMID 22848587, 2012). "Indeed, there was a weak but significant correlation of tumor volume and serum CCL18 (rho = 0.48, p<0.005)." (PMID 22848587, 2012). "Thus, we analyzed the correlation between CCL18 serum level and T-stage as a surrogate marker for tumor size." (PMID 22848587, 2012). "In contrast, high levels of CCL18 in the serum might retain T cells within the periphery and inhibits their migration into the tumor." (PMID 22848587, 2012). "There is a substantial increase in serum CCL18 levels and ROC analysis demonstrates that CCL18 might be a highly predictive serum marker to differentiate between tumor and non-tumor patients." (PMID 22848587, 2012). "The results showed that hBD-3 induced the expression of IL-1α, IL-6, IL-8, and CCL18, suggesting that hBD-3 may activate macrophages and stimulate their tumor-promoting capacity." (PMID 20544025, 2010). "Specifically, tumor-associated macrophages (TAMs) create an immunosuppressive milieu through the production of a plethora of paracrine factors (IL-6, IL-12, TNF-alpha, TGF-beta, CCL1, CCL18) promoting the acquisition by CSCs of a stem-like, invasive and metastatic phenotype." (PMID 39981232, 2025). "In our study, the upregulation of the FN1 signaling pathway between CCL18+ macrophages and endothelial cells, particularly in the non-responder group, indicated their potential role in promoting endothelial cell proliferation and tumor angiogenesis in NSCLC patients." (PMID 38730286, 2024). "Furthermore, CCL18 acts as an inducer, promoting tumor metastasis." (PMID 38511143, 2024).
tumor (continued). "Above all, CCL18/CCL3 blockade could elicit significant antitumor effects in ESCC through preventing the infiltration of tumor-associated macrophages and proliferation of ESCC cancer cells, which might be mediated by CCL3/CCR1, CCL3/CCR5 and CCL18/PITPNM3 pathways." (PMID 36850011, 2023). "In addition, some studies have found that CCL18 antagonist can block tumor metastasis." (PMID 36173487, 2023). "Notably, elevated CCL18 levels in the serum and tumor are related to a worse prognosis in patients." (PMID 38347955, 2023). "Notably, contrary to normal ECM from the same patient, tumor ECM was able to polarize human macrophages into an M2-like phenotype, anti-inflammatory, and pro-tumor, with the expression of specific markers and the secretion of anti-inflammatory cytokines, such as CCL18." (PMID 35053521, 2022). "Furthermore, propofol was confirmed to suppress HB tumor progression by regulating CCL18." (PMID 34354751, 2021). "Furthermore, PITPMN3 is also expressed on endothelial cells and upon binding CCL18 may promote angiogenesis and tumor progression." (PMID 32456359, 2020). "In addition, TAMs secrete CCL18 that facilitates angiogenesis and tumor growth in breast carcinoma." (PMID 32992449, 2020). "In addition, CCL18 also protects tumor cells from chemotherapy by increasing chemoresistance." (PMID 23349697, 2013). "This might explain the low correlation between tumor volume and serum CCL18 levels." (PMID 22848587, 2012). "Thus, increased expression of CCL18 within the tumor fosters the influx of T cells into the tumor and might therefore be protective." (PMID 22848587, 2012). "Thus, CCL18 may play a role in the recruitment and the induction of Tregs in the tumor environment and subsequently fosters the escape of the tumor from immune surveillance." (PMID 22848587, 2012). "Interestingly CCL18 shows some similarity to TGF-ß, but the role of CCL18 in the tumor environment of NSCLC is still unknown." (PMID 22848587, 2012). "This transfer reprogrammed TAMs from anti‐tumor CD5L+ to pro‐tumor TREM2+ phenotypes, increasing CCL18 secretion, reducing phagocytic activity, and impairing CD8+ T cell proliferation." (PMID 40552574, 2025). "Across all nodal stages (N0 to N3), promoter methylation levels of CCL18 and EGF remained significantly lower in tumor samples compared to normal tissue (normal: 97; N0 = 230; N1 = 242; N2 = 97; N3 = 20; p < 0.05)." (PMID 40692603, 2025). "A key limitation is the absence of functional assays to directly demonstrate the roles of CCL18 and EGF in tumor development and progression." (PMID 40692603, 2025). "Building upon the observed differential expression of CCL18 and EGF across multiple tumor types, we next focused on evaluating their expression specifically within the context of BRCA." (PMID 40692603, 2025). "To explore potential functional implications of CCL18 and EGF expression in the tumor microenvironment, we next investigated their potential roles in modulating the tumor immune microenvironment." (PMID 40692603, 2025). "CCL18 is a critical chemokine in the TME, primarily secreted by TAMs but also by CAFs and tumour cells." (PMID 40361472, 2025). "M2 expresses high levels of CD163, CD206, CCL18, and CCL22, releasing anti-inflammatory (TGF-β, IL-4, and IL-13) and inflammatory (IL-6, IL-12, and TNF-α) factors, as well as tumor-promoting arginase-1 and VEGF, modulated by TME signals." (PMID 40940877, 2025). "This interaction triggers SRC family kinase (SFK) signaling in the TAMs, leading to the secretion of CCL18 into the TME, which plays a crucial role in promoting tumor cell dissemination." (PMID 39911389, 2025). "This revitalization was characterized by reduced fractions of CCL18+ and SPP1+ macrophages alongside antitumor phenotypic remodeling of tumor-infiltrating macrophages and CD8+ T cells." (PMID 41409288, 2025).